MAML1 (mastermind like transcriptional coactivator 1)
Diseases named in the same sentence as MAML1 in open-access papers (continued):
Sharing a sentence is not in itself a finding about the gene and the disease.
tumor (28 papers, 2013 to 2025). "Microarray gene expression analysis further identified a DTX1-specific, MAML1-independent transcriptional program - including microRNA-21- which is functionally linked to the changes in tumor cell aggressiveness." (PMID 23451269, 2013). "The results revealed that HCC tumours with MAML1 knockdown had a weaker capacity to colonize the lungs than control tumours did." (PMID 41345959, 2025). "Ki67 staining also verified that MAML1-depleted HCC tumours had fewer positive cells, implying an inhibition of cancer proliferation." (PMID 41345959, 2025). "Further analyses revealed that MAML1 expression was further increased when HCC developed into high-grade/stage tumours." (PMID 41345959, 2025). "IHC staining assays confirmed MAML1 was successfully reduced in shMAML1 SK-Hep1 tumours as compared to the PLKO counterparts." (PMID 41345959, 2025). "In contrast, cutaneous HPV E6 proteins preferentially bind to the LXXLL motif-containing binding partner, MAML1, to inhibit tumor suppressive NOTCH signaling." (PMID 38920397, 2024). "All these results indicated that miR-184-3p functioned as a tumor suppressor in TNBCs by targeting MAML1." (PMID 37957722, 2023). "The E6 protein of β-HPV can target many pathways or proteins such as p300, MAML1 or Notch, which in particular has tumor suppressor gene functions in epithelial cells." (PMID 32348362, 2020). "Then, the tissues were subjected to H&E staining for evaluating tumor metastasis or to immunohistochemical staining for detecting MAML1 expression." (PMID 31660998, 2019). "The cell proliferation rate, as measured by the percentage of Ki-67+ tumor cells, was increased in tumors from the miR-133a-3p-knockdown xenografts and decreased in tumors from the MAML1-knockdown xenografts." (PMID 31660998, 2019). "There were also significant correlations between MAML1 expression, sex, grade, depth of tumor invasion, and stage of ESCC samples." (PMID 31470870, 2019). "A cluster of Mastermind-like (MAML) genes, including MAML1, MAML2, and MAML3, encodes transcriptional co-activators for various signal pathways such as Notch signaling and tumor suppressor pathway activated in multiple cancers." (PMID 28249600, 2017). "Functionally, MAML1 promoted tumor malignancy by regulating STAT3 activity." (PMID 41345959, 2025). "We also constructed a tail-vein metastasis model to examine whether targeting MAML1 could suppress HCC tumour metastasis." (PMID 41345959, 2025). "Significantly, the MAML1 was strongly correlated with HCC tumor stage." (PMID 41345959, 2025). "To test whether MAML1 inhibition has the ability to suppress HCC tumour growth, we inoculated PLKO and shMAMLl1 SK-Hep1 cells into the flank area of 6-week-old male mice and monitored tumour growth weekly." (PMID 41345959, 2025). "Why would an Alpha E6 protein not evolve to both interact with E6AP to target cellular proteins for degradation, and simultaneously also interact with MAML1 to repress the Notch tumor suppressor pathway in squamous epithelia (like a Beta or Gamma genus E6 protein)?" (PMID 29281732, 2017). "Additionally, MAML1-knockdown attenuated the effect of miR-133a-3p-knockdown on tumor growth." (PMID 31660998, 2019). "Moreover, we confirmed that MAML1 could drive HCC tumour growth in vivo, which could be blocked by the inhibition of STAT3 signaling either by ruxolitinib administration or shRNA, suggesting that the tumour-promoting role of MAML1 is dependent on STAT3 signaling." (PMID 41345959, 2025). "Conversely, MAML1 upregulation enhances Notch1 and Gli1 expression, driving accelerated TNBC tumor growth and faster multiorgan metastasis in vivo." (PMID 41272291, 2025).
tumor (continued). "Instead, beta HPV E6 proteins interact with the Mastermind-like transcriptional coactivator 1 (MAML1) to inhibit signaling of NOTCH, a tumor suppressor in squamous epithelial cells." (PMID 39772099, 2024). "We found that similar to what has been reported for HPV5 and 8 E6, MmuPV1 interacts with MAML1 and TGF-β R-SMADs, thereby inhibiting these two important tumor suppressor pathways." (PMID 28107544, 2017). "Using tumor samples collected from the Lgr5-specific Ythdf1cki mouse model, qPCR analysis revealed that YTHDF1 knock-in increased the expression of NOTCH1 downstream targets, including MAML1, MAML2, HES1, and HEY1." (PMID 41423446, 2025). "An increased level of MAML1 was clearly observed in HCC tumours compared with that in the noncancer cohorts." (PMID 41345959, 2025). "Indeed, forced expression of miR-138–2 suppressed the tumor growth in vivo along with a significant down-regulation of NOTCH1, MAML1, APH1A and HES1." (PMID 36973704, 2023). "MAML1 and β-catenin interact each other both in vitro and in vivo, suggesting that MAML1 is recruited by β-catenin on promoters containing TCF-binding sites to reinforce efficiently the transcriptional activation and to trigger tumor transformation." (PMID 33425921, 2020). "In another study we have also shown that there wre significant correlations between MAML1 and PYGO2 as the main components of NOTCH and WNT signaling transcriptional machineries respectively and tumor depth of invasion and size among a group of Iranian ESCC cases." (PMID 31470870, 2019). "Although, there was not any MAML1 expression in normal margins, 59% of tumor samples showed MAML1 protein overexpression." (PMID 31470870, 2019). "Supporting this, expression of a dominant negative Notch co-activator, MAML1, suppressed heterotopic tumor growth in a wild-type environment, suggesting that the Notch pathway plays a critical role in this process." (PMID 25592291, 2015).
cancer (17 papers, 2010 to 2025). A tumor composed of atypical neoplastic, often pleomorphic cells that invade other tissues. "Finally, it is noteworthy that in silico analysis reveals the presence of some MAML1 mutations in several cancer cell lines." (PMID 33425921, 2020). "H&E staining showed that the histopathology of tumors formed in the miR-133a-3p-knockdown xenografts exhibited morphologic characteristics of poorly differentiated carcinoma and increased cell mitosis, whereas MAML1-knockdown attenuated these effects." (PMID 31660998, 2019). "Intriguingly, these observations may suggest that the miR-30c-MAML1-YAP/TAZ axis may be a potential therapeutic target for developing novel cancer treatment." (PMID 33425921, 2020). "Interestingly, BPV-1 and β-HPV can sequester MAML1 through E6/MAML1 interaction, able to inhibit epithelial differentiation and to promote cancer progression in epithelial cells." (PMID 33425921, 2020). "Thus, MAML1 appears to function in transcriptional coactivation in a multitude of cellular processes and human diseases, including cancers." (PMID 31660998, 2019). "Furthermore, the ability of MmuPV1 E6 to bind MAML1 is necessary for wart and cancer formation in experimentally infected mice." (PMID 29568286, 2018). "Interestingly, co-transfection of HIF-1α or HIF-2α with full-length MAML1 into cancer cells induced ICN3-mediated Notch signaling dramatically, indicating a strong synergy between HIF factors and MAML1 in the activation of Notch pathway." (PMID 20010940, 2010). "In this regard, it is intriguing the observation that an aberrant MAML1 expression/activation may disrupt not only the directly related pathway, but also the interconnected signaling cascades, leading to an unbalanced crosstalk that culminates in a series of disorders or cancer development." (PMID 33425921, 2020). "At transcriptional level, Notch regulates Snail expression through the tripartite complex NICD-CSL-MAML-1, as demonstrated by the evidence that the dominant-negative mutant of MAML-1 (DN-MAML-1) inhibits Snail expression and EMT in cancer cells." (PMID 29996493, 2018). "Inhibition of both TNFα and MAML1 brought the macrophage-induced MenaINV expression to baseline levels observed when cancer cells were cultured without macrophages." (PMID 37024946, 2023). "MAML1 and NOTCH ternary complex (NTC) inhibitors, such as SAHM1 and NADI-351, respectively, capable of blocking NOTCH transcriptional complex activity, have demonstrated potential anti-cancer properties." (PMID 36674902, 2023). "Given its pivotal role as interconnection point among several signaling pathways, it is not surprising that MAML1 protein is directly or indirectly involved in several disorders, including cancer." (PMID 33425921, 2020). "Beyond the recently identified role played by MAML1 in SHh and YAP/TAZ signaling pathways, it is known that MAML1 can also functionally collaborate with different transcription factors involved in cell differentiation and cancer development." (PMID 33425921, 2020). "None of the nuclear components, KDM5A, MAML1, SKIP and CBF1 showed significant expression changes between normal and cancer tissues." (PMID 25167871, 2014).
MAML1 also shares sentences with these, for which no sentence is quoted: hepatocellular carcinoma (2 papers); leukemia (2); melanoma (2); pancreatic cancer (2); acute lymphoblastic leukemia (1); brain tumor (1); breast tumor (1); clear cell sarcomas of the kidney (1); diabetes (1); endometrioid adenocarcinoma (1); esophageal cancer (1); Fanconi anemia (1); fibromatosis (1); hemangioendothelioma (1); hypogonadotropic hypogonadism (1); hypospadias (1); idiopathic pulmonary fibrosis (1); invasive breast carcinoma (1); lung carcinoma (1); Myocardial fibrosis (1); renal carcinoma (1); small cell lung carcinoma (1); spindle cell sarcoma (1); T-cell acute lymphoblastic leukemia (1); triple-negative breast carcinoma (1).